MTOR (mechanistic target of rapamycin kinase)
Diseases named in the same sentence as MTOR in open-access papers (continued):
Sharing a sentence is not in itself a finding about the gene and the disease.
tumor (continued). "Cardamonin protected the heart from oxidative damage and inflammatory injury by activating Nrf2-related cytoprotective system in cardiac muscle cells, whereas cardamonin suppressed tumor cell growth by inducing oxidative stress through NF-κB/mTOR and HIF-1α pathways." (PMID 37304865, 2023). "However, tumors have changes in PI3K mTOR signaling pathway, and mTOR also changes the availability of glucose in tumor cells by regulating glucose uptake and glycogen decomposition." (PMID 36936171, 2023). "In addition to the drugs already approved by the FDA, many other mTOR inhibitors are currently being studied in tumor models and will probably also be used in patients with TSC." (PMID 36982349, 2023). "In addition, important tumor pathways such as Wnt, MAPK, PI3K/AKT, TGF-beta, NF-kB, Notch, AMPK, JAK-STAT, PD-1/PD-L1, mTOR, Ras, TNF, HIF-1, ErbB are also associated with the risk score, and pathways and functions are correlated as well." (PMID 37884883, 2023). "According to one study, the downstream molecule of the PI3K/Akt signaling pathway, mechano/mammalian target of rapamycin (mTOR), can be involved in the regulation of multiple physiological functions of tumor cells by integrating various cellular signals in the TME." (PMID 38169723, 2023). "Furthermore, AXIN1 has been found to reduce PI3K/AKT/mTOR signaling and act as a tumor suppressor in TGCT cells." (PMID 37078359, 2023). "Moreover, the tumor’s genetic profile guides the selection of combination therapies that address multiple genetic alterations within the mTOR pathway or its interactions with other signaling networks." (PMID 37834408, 2023). "For example, the mTOR pathway can sometimes trigger anti-tumor immune responses." (PMID 37046703, 2023). "Targeting mTOR has been demonstrated as an effective strategy to inhibit tumor progression." (PMID 37248471, 2023). "Moreover, its anticancer potential was rooted in the modulation of inflammation, cell cycle, apoptosis, PI3K/Akt/mTOR pathway, angiogenesis, tumor-suppressor gene, and others cell signaling pathways." (PMID 37298670, 2023). "DEPTOR is a tumor suppressor that inhibits mTOR activity by directly binding to mTOR complexes." (PMID 37717015, 2023). "Interestingly, the tumor suppressive miR-99b-5p has been involved in regulating PI3K/AKT/mTOR activity in prostate cancer (PCa)." (PMID 37237486, 2023). "In contrast, under the simultaneous stimulation of Angpt1/2 + Neamine, no significant change was found in these indexes, further indicating that the influence of SHP-2 on the migration and invasion abilities of TEMs and tumor micro-angiogenesis is mediated by the PI3K/Akt/mTOR signaling pathway." (PMID 37304233, 2023). "Additionally, mTOR, a key regulator of cell growth and division in healthy conditions, can be inappropriately activated in tumor cells and thus promote tumor cell growth, metastasis, and invasion of fresh, healthy tissues." (PMID 37895091, 2023). "The patient’s tumor also carried VUSs in the AKT/mTOR pathway genes AKT1 and IRS2." (PMID 37202426, 2023). "Mechanistically, the tumor suppressive effect of metformin is partly dependent on mTOR inhibition." (PMID 37760498, 2023). "The cytokines secreted in BMM which are contributed to the pathogenesis of MM as IL6, VEGF and IGF activate their respective receptors expressed on MM cells through an important pathway, PI3K/AKT/mTOR, and promote tumor growth as well as resistance development to existing therapies." (PMID 37437037, 2023). "Altogether, these outcomes demonstrate that CTSG may act as a tumor suppressor gene via Akt/mTOR/Bcl2-mediated anti-apoptotic signaling inactivation, and CTSG represents a potential therapeutic target in CRC." (PMID 37151875, 2023).
tumor (continued). "YBX1 is also involved in tumor progression via the PI3K/Akt/mTOR signaling cascade." (PMID 36740668, 2023). "For example, mammalian target of rapamycin (mTOR) can convert tumor cells into fat‐like cells." (PMID 37206227, 2023). "Alpha-methyltryptophan (α-MT), an inhibitor of this transporter, induces amino acid starvation and autophagy in tumor cells by blocking SLC6A14, inhibiting mTOR signal transduction, inducing amino acid starvation, and inhibiting tumor cell growth and proliferation." (PMID 37924140, 2023). "PD-1 is able to regulate the mTOR signaling pathway, which controls tumor growth." (PMID 36759819, 2023). "In addition, metformin activates NK cells infiltrated to the tumor accompanied with high perforin production through mTOR inhibition that subsequently suppresses CXCL1 production in an AMPK-independent manner but is dependent on the mTOR and pSTAT1 pathways." (PMID 37686159, 2023). "In clinical trials, patients’ tumor growth could be diminished by mTOR inhibitor but on a temporary basis." (PMID 37386121, 2023). "It has been shown that mTOR could rewire tumor cell metabolism, and that related metabolism changes could sustain the mTOR pathway in turn." (PMID 37190313, 2023). "The c-MYC/PI3K/AKT/mTOR axis can be targeted to decrease tumor progression." (PMID 37895357, 2023). "The mammalian target of rapamycin (mTOR) is a serine/threonine protein kinase that turns into complexes with other molecules in tumor cells, including mTOR complex 1 (mTORC1) and mTOR complex 2 (mTORC2), and both of them can affect the function of immune cells and promote the growth of tumor cells." (PMID 38264667, 2023). "The mTOR inhibitors promoted blood-vessel normalization, leading to a reduction in tumor hypoxia." (PMID 38203186, 2023). "Notably, inhibition of the mTOR signalingpathway by t-LRR not only inhibited tumor glycolysis but also facilitatedthe repolarization of TAMs toward M1-like phenotypes." (PMID 37901179, 2023). "This drug blocks the mTOR pathway and interferes with tumor glycolysis and thus tumor growth." (PMID 36624636, 2023). "The phosphorylated AKT (p-AKT) can activate multiple downstream signaling molecules, inhibit tumor cell autophagy through mTOR, phosphorylate MADD, caspase-3, caspase-9, phosphorylate FOXO-1 to control the cell cycle, and promote tumor cell growth and/or metastasis." (PMID 37070074, 2023). "In addition to causing tumor cell growth, proliferation, and survival, the PI3K/mTOR pathway also plays a crucial role in making the tumor resistant to conventional therapies, such as radiotherapy and chemotherapy." (PMID 37046703, 2023). "Interestingly, the inhibition of GLI1/2 and PI3K/mTOR seems to produce a synergistic effect on apoptosis induction and tumour growth reduction in RMS." (PMID 36765685, 2023). "The binding of CCL5 to CCR5 on cancerous epithelial cells induces tumor growth via several signaling pathways, including the mammalian target of rapamycin (mTOR), the pathway activation of the Janus kinase signal transducer, and the activator of transcription (JAK-STAT) pathway." (PMID 37759462, 2023). "The PI3K/Akt/mTOR pathway stimulates anabolic processes in tumor cells." (PMID 37958470, 2023). "Furthermore, gene function analyses indicated that multiple signaling pathways involving tumor oncogenesis and development enriched, such as mTOR, cell cycle, MAPK, Notch, Hedgehog, FGF, and PI3K-Akt signaling pathways." (PMID 37277853, 2023). "Previous studies had shown that activation of mTOR promotes tumor growth and metastasis." (PMID 37061713, 2023).
tumor (continued). "Therefore, the transmission and activation of mTOR are vital to the growth and metabolic activity of tumor cells." (PMID 38139250, 2023). "Furthermore, mTOR enhances the translation of HIF1α, the master oxygen sensing molecule, which fosters multiple tumor-promoting mechanisms such as angiogenesis, metastasis, cell proliferation and glucose metabolism." (PMID 37786827, 2023). "Indeed, several reports support the superior efficacy of combining inhibitors of the PI3K/AKT/mTOR and AR signaling pathways in reducing tumor growth, both in vitro and in vivo preclinical studies." (PMID 36768610, 2023). "PHGDH may be associated with tumorigenic EMT through its association with The MAPK signaling pathway interacting with PI3K/AKT/mTOR signaling pathway may jointly promote tumor development, suggesting that PHGDH may act through different mechanisms." (PMID 36803157, 2023). "Down-regulation of the Akt/mTOR pathway in the early stages of tumor growth could lead to tumor growth inhibition." (PMID 36721812, 2023). "Furthermore, the Co-Sp decreased the phosphorylation of PI3K, AKT, and mTOR in cells and tumor tissues." (PMID 37313467, 2023). "PRS could enhance the intracellular drug delivery and tumor-targeting delivery, synergistically inhibiting tumor cell proliferation by interrupting the mTOR pathway." (PMID 37896137, 2023). "PIK3CA amplification or mutations promote tumour infiltration and activate the PI3K/AKT/mTOR pathway, which suggests that PI3K/AKT/mTOR pathway activation might be related to resistance to 3rd-generation EGFR-TKIs." (PMID 37897649, 2023). "However, the regulation of ROS is often known to maintain cellular stability and enhance tumor progression by modulating various proliferative pathways such as PI3K/AKT/mTOR pathway, MAPK pathway and Wnt signalling pathway." (PMID 37025487, 2023). "Moreover, the PI3K/AKT/mTOR pathway is involved in tumour cell growth, proliferation, metastatic progression, and angiogenesis, as well as being associated with several disorders, including tumours and neurodegenerative disorders." (PMID 37174088, 2023). "Co-expression involving 126 lncRNAs interacting with 14 mRNAs of the mTOR pathway was found, which may support the pathogenesis of the gonadotrophin tumor." (PMID 37446128, 2023). "However, new immunosuppressive drugs, such as mycophenolate mofetil (MMF) and mechanistic target of rapamycin (mTOR), can reduce tumor growth." (PMID 37841427, 2023). "Higher phosphorylated mTOR expression was associated with the absence of a tumor capsule, the presence of distant metastases, the persistence of disease, and NRAS mutation." (PMID 36980552, 2023). "Further studies in the upcoming years may help clarify the specific TSC/mTOR gene alternations and identify other factors (genetic, epigenetic, or host factors) that influence tumor development." (PMID 37627070, 2023). "In addition, the nanocarriers can be designed with stimuli-responsive properties that release the mTOR inhibitor in response to specific cues within the tumor microenvironment." (PMID 37834408, 2023). "Thus, suppressing and inhibiting mTOR signaling can decrease the survival rate and growth of tumor cells." (PMID 36721212, 2023). "In addition, inhibiting glutamine metabolism into GSH combined with the mTOR inhibitor can enhance tumor cell death." (PMID 37924140, 2023). "Other mechanisms on which Metformin play an action are: mammalian target of rapamycin (mTOR, crucial to tumor cell metabolism), adenosine mono-phosphate-activated protein kinase (AMPK), mitochondrial glycerophosphate dehydrogenase (mGPDH), and the nuclear factor kB (NF-kB)." (PMID 38146457, 2023). "Similarly, another study on 43 resected pancreatic NENs showed that liver metastases showed overexpression of the mTOR pathway in comparison to the primary tumour." (PMID 36980746, 2023).
tumor (continued). "Everolimus is a first‐generation mTOR inhibitor that binds the intercellular receptor FKB12, which then binds and preferentially inactivates the mTOR protein kinase complex 1 (mTORC1) slowing tumor growth, limiting metastatic and local spread, and inhibiting DNA damage repair." (PMID 37644890, 2023). "Moreover, the activation of the mTOR pathway was related to tumor differentiation and vascular invasion in HCC patients." (PMID 37189787, 2023). "The phosphatidylinositol-3-kinase (PI3K)/AKT/mammalian target of rapamycin (mTOR) signaling pathway has multiple functions related to the regulation of various biological behaviors in tumor cells and plays a crucial role in the occurrence and development of NSCLC." (PMID 37974250, 2023). "In murine tumor models, tumor-infiltrating MDSCs have more active glycolysis and mTOR signaling." (PMID 38008741, 2023). "The PI3K/AKT/mTOR pathway is a well-established tumor growth–promoting pathway in ARPC." (PMID 37823778, 2023). "Notably, the PI3K/AKT/mTOR signaling pathway exhibited significant enrichment in subtype A, which is recognized for its involvement in the regulation of the tumor immune microenvironment." (PMID 37152048, 2023). "Importantly, an mTOR gene signature that discriminates between normal and tumor prostate and that is predictive of progression has been proposed." (PMID 36768610, 2023). "All three compounds reduced metastasis by inhibiting the mTOR signalling pathway and may affect tumour growth and migration steps (steps 1–2 and 4)." (PMID 36983973, 2023). "This staining pattern suggests that full engagement of the mTOR response may preferentially occur in the tumor microenvironment." (PMID 37262067, 2023). "Another crucial pathway in BC is the PI3K/Akt/mammalian target of rapamycin (mTOR) signaling, wherein activating PIK3CA mutations, occurring in about 40% of hormone receptor HR+/HER2− MBCs, are driver events for tumorigenesis and tumor progression." (PMID 37372340, 2023). "Higher expression of NEU1 is associated with increased proliferation, migration, and lower levels of B cells, T-cells, and natural killer (NK) cells, regulating several tumor-related proteins and pathways, such as lysosome, spliceosome, and mTOR signaling pathways." (PMID 37601653, 2023). "However, 2-DG and 2ME2 did not significantly enhance the effect of EVE, these results suggest that glucose deprivation inhibits TAMs-mediated tumor metastasis through the mTOR-HIF-1α glycolytic pathway." (PMID 37884960, 2023). "Deregulation of mTOR signaling was also involved in tumor formation and progression." (PMID 37239855, 2023). "Therefore, we also suspected that there were three other possible reasons for suppressing tumor growth in the combination of mTOR inhibitors and PCSK9 inhibitors which would be explored in greater detail in our future studies." (PMID 37896137, 2023). "More importantly, it was observed that the inhibition of mTOR by pharmacological VC supplementation in vivo produces positive therapeutic responses in tumor growth, while HMOX1 deficiency rescues the inhibitory effect of pharmacological VC on tumor growth." (PMID 36787291, 2023). "In addition, ROS can also regulate some important signal transduction networks associated with tumor progression, such as the NF-kB signaling pathway and the PI3K/mTOR signaling pathway." (PMID 37138031, 2023). "Promising results have been observed in mTOR inhibitor tests against tumor cells." (PMID 37465088, 2023). "Importantly, high activation of mTOR in tumor cells will reprogram the cell metabolism by altering the availability of metabolic enzymes." (PMID 37304865, 2023). "Despite these anti-tumor effects, mTOR inhibitors are rarely given immediately after solid organ transplantation, because they have been associated with the increased incidence of wound healing complications and severe side effects, including peripheral edema and hypertriglyceridemia." (PMID 37887285, 2023).
tumor (continued). "While this approach could be beneficial for the patient, it could also be beneficial for the tumour: if increased dietary protein intakes induce an increased protein synthesis in the tumour, via the same mTOR signalling, it could thereby promote tumour growth." (PMID 37667552, 2023). "Targeting the CCL8/CCR5/mTOR pathway is a promising target for future tumor treatment." (PMID 38136340, 2023). "Promising results have been seen from testing mTOR inhibitors against tumor cells." (PMID 37333043, 2023). "In conclusion, ESM1 may promote angiogenesis in CRC by activating the PI3K/Akt/mTOR pathway, thus accelerating tumor progression." (PMID 37100467, 2023). "It should be noted that anti-PD-L1 may also directly suppress tumor growth by disrupting mTOR activity and glycolysis." (PMID 37434177, 2023). "New mTOR inhibitors have demonstrated anti-tumor activity in clinical studies, and mTOR inhibition may be capable of inhibiting malignant cells and essential tumor-development in transplant recipients." (PMID 37200246, 2023). "Tesirolimus, an mTOR inhibitor, hinders tumor angiogenesis by disrupting VEGF production." (PMID 38069225, 2023). "Interestingly, a study showed that treatment with rapamycin, a mTOR inhibitor, significantly reduced the tumor size in mice transplanted with HPV-positive oral cells." (PMID 37237486, 2023). "Similarly, the studies showed that B7-H3 downregulation or inhibition can make tumor cells more sensitive to inhibitors of PI3K/Akt/mTOR and Ras/Raf/MEK signaling pathways." (PMID 37110590, 2023). "Likewise, the downregulation of PTEN also plays a role in the activation of the PI3K/AKT/mTOR pathway that regulates similar tumor phenotypic activities." (PMID 37205308, 2023). "So far, it is known that the mTOR signaling cascade can affect HIF-1α translation and stimulation of this pathway, for example by growth factors, hormones, or oncogenes/tumor suppressor mutations, which can lead to HIF-1α synthesis, even under normoxic conditions." (PMID 37371055, 2023). "Thus, inhibiting the mTOR-signaling pathway by adding everolimus to vinorelbine can attenuate tumor growth and sensitize vinorelbine-resistant HCC tumors." (PMID 38203186, 2023). "The PI3K/AKT/mTOR signaling pathway promotes the survival and proliferation of tumor cells." (PMID 38239705, 2023). "Similar to NK cells, an increase in mTOR activity in tumor infiltrating CTLs in HIF-1αΔNφ mice may be expected." (PMID 36614196, 2023). "Activation of the mTOR signaling pathway can accelerate neoplasm growth and metastasis." (PMID 37626304, 2023). "In fact, the long-term use of the mTOR inhibitor Everolimus to inhibit tumor growth and spread has been unsuccessful due to resistance caused by genomic instability induced by long-term treatment with Everolimus, but the underlying mechanisms are currently unclear." (PMID 37781700, 2023). "Genetic amplification of DSTYK sustains mTOR-mediated autophagy dependency in tumor cells." (PMID 37370686, 2023). "We previously reported that orlistat exhibited anti-proliferative activity against EC cells in vitro by inducing cell cycle G1 arrest and cellular stress and inhibiting fatty acid metabolism and the mTOR pathway, indicating that orlistat deserves further anti-tumor studies in vivo for EC." (PMID 37601677, 2023). "The inhibitory effects of ONC201 and ONC206 on tumor growth are thought to be via their effects on the PI3K/AKT/mTOR pathway as well as DNA repair, suggesting that ONC201 and ONC206 may be logical therapeutic partners for PARP inhibition in EC." (PMID 37069726, 2023). "The mTOR pathway has previously been shown to be important for polarity-impaired Ras-driven tumour growth in Drosophila, and its inhibition by trametinib that we observed in our study is likely to contribute to the G1 cell cycle arrest observed upon trametinib treatment." (PMID 36861754, 2023). "As a downstream effector of PI3K/Akt, mTOR is usually hyperactive in various tumor types." (PMID 36849435, 2023).